ADAM18 (ADAM metallopeptidase domain 18)
Description:
Sperm surface membrane protein that may be involved in spermatogenesis and fertilization. This is a non catalytic metalloprotease-like protein (By similarity).
Synonyms: tMDCIII; ADAM27
Tractability: Antibody: UniProt predicts a signal peptide or a membrane-spanning region; its Gene Ontology location is reachable by antibodies, with medium confidence.
Gene: Protein-coding gene on chromosome 8 (39,584,489 to 39,730,065, forward strand). Ensembl gene ENSG00000168619.
Subcellular location: Membrane
Gene Ontology:
Molecular function: metalloendopeptidase activity; metallopeptidase activity
Biological process: binding of sperm to zona pellucida; cell adhesion; male gonad development; proteolysis; spermatogenesis
Cellular component: membrane; plasma membrane
Genetic constraint (gnomAD): Loss-of-function variants: 69 observed, 53.18 expected, observed/expected ratio (o/e) 1.3, 90% interval 1.07 to 1.59. The upper end of that interval is the gene's LOEUF score, 1.59, which puts it in group 6 of 6, group 1 being the genes least tolerant of losing a copy. Missense variants: 642 observed, 588.36 expected, observed/expected ratio (o/e) 1.09, 90% interval 1.02 to 1.16. Synonymous variants: 210 observed, 198.52 expected, observed/expected ratio (o/e) 1.06, 90% interval 0.94 to 1.19.
Homologues: Orthologues: chimpanzee ADAM18 (98% identical), macaque ADAM18 (94% identical), pig ADAM18 (72% identical), rabbit ADAM18 (70% identical), mouse Adam18 (60% identical), rat Adam18 (60% identical), tropical clawed frog XB990656 (29% identical), zebrafish adam9b (28% identical), Caenorhabditis elegans unc-71 (24% identical), Drosophila melanogaster mmd (19% identical), zebrafish adam10a (18% identical), Caenorhabditis elegans sup-17 (16% identical), and 2 more. Paralogues in human: ADAM32 (40% identical), ADAM2 (40% identical), ADAM9 (33% identical), ADAM33 (27% identical), ADAM12 (27% identical), ADAM29 (26% identical), ADAM20 (26% identical), ADAM21 (26% identical), ADAM30 (25% identical), ADAM19 (25% identical), ADAM23 (25% identical), ADAM28 (24% identical), and 8 more.
Diseases named in the same sentence as ADAM18 in open-access papers:
ADAM18 is named in the same sentence as 4 diseases in open-access papers, as found by Europe PMC text mining. Sharing a sentence is not in itself a finding about the gene and the disease. The quoted sentences say what the papers report.
COVID-19 (1 paper, 2022). A disease caused by infection with severe acute respiratory syndrome coronavirus 2. "We found that the expression of the antiviral genes negatively correlated (except ADAM7, ADAM11, ADAM12, ADAM18, ADAM20, and ADAM29) with the HRCT score of the COVID-19 patients suggesting association of increased antiviral response with decreased disease severity." (PMID 36532041, 2022).
cancer (3 papers, 2023 to 2024). A tumor composed of atypical neoplastic, often pleomorphic cells that invade other tissues. "Pan-cancer SNV analysis revealed relatively high mutation frequencies in ADAM29, ADAM7, and ADAM18, with mutations predominantly observed in SKCM and UCEC." (PMID 39346916, 2024). "The SCNA comprised focal losses in 8p11.22 including the metallopeptidase genes ADAM18 and ADAM32 in 22% of lFL (q = 1.4E-15) and focal gains affecting 11q24.3 harboring cancer-associated genes ETS1 and FLI1 in 22% of lFL (q = 2E-27)." (PMID 37563306, 2023).
ADAM18 also shares sentences with these, for which no sentence is quoted: metastatic melanoma (1 paper); metastatic tumors (1).